CD27 (CD27 molecule)
Diseases named in the same sentence as CD27 in open-access papers (continued):
Sharing a sentence is not in itself a finding about the gene and the disease.
primary Sjögren’s syndrome (11 papers, 2005 to 2024). "Mutated CD27- B cells have, however, been described in a study by Hansen and colleagues in patients with Sjögren's syndrome." (PMID 15987473, 2005). "Lower CD6+ memory B cells in patients with primary Sjogren’s syndrome (pSS), was reported to be due to the transmigration of CD27+ memory B cells into salivary glands of pSS patients." (PMID 39026665, 2024). "In primary Sjögren’s syndrome, CD27+ memory B cells, marginal zone B cells, plasmablasts, and plasma cells are the key subsets of B cells." (PMID 34440626, 2021). "Curiously, in primary Sjögren’s syndrome, the proportion of IgM-only memory B cells (IgDnegIgM+ among CD27+ B cells) is increased compared with healthy controls." (PMID 23087687, 2012). "Reports differ on whether PB CD27+ B cells are lower or higher in primary Sjögren’s syndrome." (PMID 23087687, 2012).
psoriasis (11 papers, 2021 to 2026). An autoimmune condition characterized by red, well-delineated plaques with silvery scales that are usually on the extensor surfaces and scalp. "The finding that the CD70/CD27 signaling pathway serves as an important link between the two provides a new theoretical basis for unraveling the molecular mechanisms of DCs in psoriasis." (PMID 38596682, 2024). "Patients with psoriasis exhibit a decreased frequency of CD27(+) memory B cells, contrary to observations in atopic dermatitis (AD), which has a predominantly Th2 response." (PMID 38596682, 2024). "Our data indicate that DCs, particularly through the CD70/CD27 pathway, mediate inflammatory responses in psoriasis by influencing other cells, especially T cells." (PMID 38596682, 2024). "CD19(+)CD27(+)CD24(high) Breg cells exhibit reduced expression in psoriasis and psoriatic arthritis patients, correlating inversely with Psoriasis Area and Severity Index (PASI) scores." (PMID 38596682, 2024). "It has been reported that PD-L1-Fc inhibits anti-CD3-induced IL-17A production in CD27–Vγ1– γδ T cells and shows great potential for the treatment of psoriasis in animal experiments." (PMID 34354596, 2021). "A recent study demonstrated that the percentage of CD19+CD27+CD24 (high) memory regulatory B cells was inversely correlated with the severity of psoriasis." (PMID 34354596, 2021). "Notably, consistent with our previous findings, gene expression analysis confirmed the specific expression of CD70 in cluster 1 DCs, providing further support for the significant involvement of the CD70/CD27 signaling pathway in psoriasis development." (PMID 38596682, 2024). "Our data imply that certain B-cell panels, such as CD20−AC, unsw mem %lymphocyte, CD20− %lymphocyte, CD20 on IgD+ CD38−, CD27 on IgD+ CD24+, CD27 on IgD− CD38br, CD27 on IgD− CD38dim, CD38 on naive-mature B cell, and IgD on IgD+ CD38−unsw mem, are related to an elevated risk of psoriasis." (PMID 38558803, 2024). "The regulatory influence of dendritic cells (DCs) on T cells through the CD70/CD27 signaling pathway may emerge as a significant facet of the inflammatory response in psoriasis." (PMID 38596682, 2024). "Moreover, CD27 expression has been reported to be inversely correlated with Treg IL-17 production in the skin of patients with psoriasis and hidradenitis suppurativa, suggesting the role of CD27 in regulating Treg plasticity in inflammatory tissue." (PMID 37874660, 2023). "Serum soluble CD27 was downregulated upon treatment of psoriasis." (PMID 35300124, 2022). "Therefore, we hypothesized that DCs are involved in the pathogenesis of psoriasis by regulating T cells via the CD70/CD27 signaling pathway." (PMID 38596682, 2024). "Moreover, psoriasis patients demonstrate reduced expression of CD27 and CD28 on skin T cells." (PMID 38596682, 2024). "The role of co-signaling molecules in psoriasis is recognized, mainly including the co-stimulatory molecules CD28, CD40, OX40, CD27, DR3, LFA-1, and LFA-3 and the co-inhibitory molecules CTLA-4, PD-1, and TIM-3." (PMID 34354596, 2021). "However, Vγ4+ extrathymic precursor cells (CD27+ CD122-) in bone marrow/spleen/lymph node have been identified and can differentiate into γδT17 cells upon inflammatory conditions such as EAE and psoriasis." (PMID 38239368, 2023). "Efalizumab, a humanized monoclonal antibody against LFA-1, has shown a positive response to psoriasis through potently inhibiting the proliferation and cytokine production of human T cells by downregulating the co-stimulatory molecules ICOS, OX40, CD27, and 4-1BB." (PMID 34354596, 2021). "To date, there are no drugs on targeting the CD27:CD70 pathway for the treatment of psoriasis." (PMID 34354596, 2021). "Cytometry by time-of-flight analysis of PBMCs from psoriasis patients and healthy controls showed comparable frequency of terminally differentiated effector memory (TEMRA) CD8 T cells, which are a subset of CD45RO-CD45RA double-positive T cells lacking CD27 expression." (PMID 40391222, 2025).
chronic lymphocytic leukemia (10 papers, 2009 to 2025). "Among them, CD27 on plasmablast/plasma cell (PB/PC) was a mediator of the positive association of arginine to glutamate ratio with chronic lymphocytic leukemia, with a mediator ratio of 14.60% (95% CI=1.29-28.00%, P=3.17 × 10-2)." (PMID 39386202, 2024). "Chronic lymphocytic leukemia (CLL) is characterized by the accumulation of monoclonal mature B cells with a CD5+CD19+CD20dimIgdimCD23+CD43+CD27+ surface phenotype in the circulation." (PMID 29069762, 2017). "In a previous report, metalloprotease inhibitors were shown to block the release of CD27 and enhance the immune stimulatory activity of chronic lymphocytic leukemia cells." (PMID 19412542, 2009). "Chronic lymphocytic leukemia has traditionally been considered a malignancy originating from oncogenic transformation of a mature antigen-experienced B cell with a gene expression profiling related to normal CD27+ memory B cells." (PMID 29998084, 2018).
ovarian carcinoma (10 papers, 2014 to 2025). A malignant neoplasm originating from the surface ovarian epithelium. "A Phase 1/2 study of varlilumab (anti-CD27) with nivolumab demonstrated good tolerance and clinical activity, particularly in ovarian cancer." (PMID 40236693, 2025). "For CD70, which forms a molecular pathway with CD27, we demonstrated this increased concentration in the peritoneal fluid of ovarian cancer patients." (PMID 35204342, 2022). "We conclude that CD27 should be considered as a potential biomarker in the diagnosis of ovarian cancer." (PMID 35204342, 2022). "In summary, as this study demonstrates, CD27 can be used as a biomarker to distinguish ovarian cancer from benign ovarian lesions, as it has a specificity of 84% when the cut-off is 120.6 pg/mL." (PMID 35204342, 2022). "Our study demonstrated significantly higher levels of CD27 in patients with ovarian cancer, both in serum and peritoneal fluid, which, in comparison with previous studies, shows a new clinical aspect of this marker." (PMID 35204342, 2022). "We observed a similar population (IgD−CD27−) but also a significant increase of classical IgD−CD27+ memory B cell subset suggesting that a down regulation of CD27 is less frequent in colorectal cancer than in ovarian cancer." (PMID 25026291, 2014). "CD27 has been used for biomolecular characterization of ovarian cancer in previous studies." (PMID 35204342, 2022). "CD27, determined in serum, is an unfavorable prognostic factor for ovarian cancer." (PMID 35204342, 2022). "BTLA and CD27 are unfavorable prognostic factors for ovarian cancer." (PMID 35204342, 2022). "CD27 should be considered as a potential biomarker in the diagnosis of ovarian cancer." (PMID 35204342, 2022). "In addition, CD27-bearing C4 CAR-T cells significantly controlled the tumor growth in metastatic intraperitoneal human ovarian cancer model." (PMID 26101914, 2015). "The median concentrations of the studied proteins (BTLA, CD27, CD28 and CD80) were statistically significantly higher in serum of patients in the ovarian cancer group (group A) compared to serum concentrations in patients with benign ovarian lesions (group B)." (PMID 35204342, 2022). "Statistically significant higher median serum levels of CD27 and CD80 proteins were found in highly advanced ovarian cancer (stage III–IV) compared to low advanced ovarian cancer (stage I–II) (p = 0.02 and p = 0.03, respectively)." (PMID 35204342, 2022). "The cutoff values for BTLA, CD27, CD70, CD28 and CD80 that were elevated in the serum of patients with ovarian cancer were calculated using ROC curve analysis." (PMID 35204342, 2022).
type 1 diabetes (10 papers, 2015 to 2024). "Similarly, serum CD27 levels were strongly associated with kidney dysfunction and a low glomerular filtration rate in type 1 diabetes." (PMID 38137543, 2023). "Using this approach, we detected insulin-binding B cell bias towards CD27- memory and CD27+ memory subsets in pre-symptomatic type 1 diabetes donors." (PMID 34234784, 2021). "Expression of the activation marker CD27 on MAIT cells was increased in participants with recent-onset type 1 diabetes compared with healthy donors (p = 0.052)." (PMID 34350463, 2021). "Collectively, these analyses infer that the observed increase in CD8−CD27− MAIT cells in children with type 1 diabetes probably results from a proportional shift towards an increased frequency of DN CD27− MAIT cells." (PMID 32880687, 2020). "However, slow progressors exhibited increased expression of CD95 among B cells with a switched memory phenotype (CD27+, IgD−) compared with healthy donors (p < 0.05), in contrast to individuals with newly diagnosed or long-standing type 1 diabetes." (PMID 32157332, 2020). "It is known that marginal zone (MZ) B cells circulate in human blood as IgM+IgD+CD27+ B cells and the expansion of the MZB cell compartment has been observed in type 1 diabetes murine model." (PMID 39011037, 2024). "Of the MAIT cell alterations observed here, decreased expression of CD27 and production of IFN-γ have also been reported by others in patients with type 1 diabetes." (PMID 32880687, 2020). "A disease-linked phenotype was detected in individuals with long-standing type 1 diabetes, characterised by reduced C-X-C motif chemokine receptor 3 (CXCR3) expression on switched (CD27+IgD−) and unswitched (CD27intermediateIgD+) memory B cells." (PMID 29881878, 2018). "In contrast, no disease-specific alterations in the B cell compartment were detected in another study, designed to quantify the expression levels of CD19, CD24, CD27, CD38, IgD and IgM in individuals with type 1 diabetes and age- and sex-matched healthy donors." (PMID 29881878, 2018). "To evaluate the phenotypic characteristics of naive and memory B cells in individuals with type 1 diabetes, we developed a polychromatic flow cytometry panel incorporating a viability dye and monoclonal antibodies specific for CD3, CD19, CD21, CD24, CD27, CD38, CD45R/B220, CD95, CXCR3 and IgD." (PMID 29881878, 2018). "Instead, we found that CD95 expression was reduced on switched CD27+IgD− memory B cells in individuals with long-standing diabetes, consistent with the findings of a recent study by Hanley and colleagues, who also reported lower frequencies of CD24++CD38++ B cells in people with type 1 diabetes." (PMID 29881878, 2018). "In individuals with recent-onset type 1 diabetes, we demonstrated that MAIT cells harboured an activated profile (CD25 and CD27 upregulation) without major alterations in cell homeostasis and function." (PMID 34350463, 2021).
Hodgkins lymphoma (9 papers, 2016 to 2024). A heterogeneous group of malignant lymphoid neoplasms of B-cell origin characterized histologically by the presence of Hodgkin and Reed-Sternberg (HRS) cells in the vast majority of cases. "Targeting the CD27L-CD27 axis might be a therapeutic strategy given the observation that patients with CD27L or CD27 mutations and deletions are at a higher risk of developing Hodgkin lymphoma." (PMID 33381115, 2020). "Interestingly, Abolhassani reported two family members with genetic abnormalities in the CD70- CD27 signaling cascade associated with clinical features of AA, Behcet's disease, recurrent viral pneumonia, central nervous system infection, and Hodgkin lymphoma induced by Epstein–Barr virus." (PMID 35300124, 2022). "Interestingly, the Hodgkin lymphoma therapeutic target CD27 was expressed at lower level with TES1m rescue but more highly expressed in cells with TES2m rescue, suggesting that TES1 and TES2 signaling may jointly balance its expression." (PMID 38009935, 2023). "In Hodgkin lymphoma, a different expression pattern was observed whereby Reed-Sternberg cells show high CD70 levels but lack the expression of CD27." (PMID 34991665, 2022).
leukemia (9 papers, 2016 to 2022). A malignant (clonal) hematologic disorder, involving hematopoietic stem cells and characterized by the presence of primitive or atypical myeloid or lymphoid cells in the bone marrow and the blood. "HDs may provide a more functional T cell product and could be screened for a T cell phenotype linked with more potent anti-leukaemia activity such as CD8+CD27+CD45RO– associated with improved response in the setting of CLL." (PMID 30275435, 2018). "In leukemia, it is seen that the CD27 signaling on AML and CML LSCs leads to induction of the Wnt pathway, an important pathway for self-renewal." (PMID 34991665, 2022). "The importance of the CD27/TNIK/Wnt signaling pathway has been documented before in leukemia stem cells." (PMID 32242021, 2020). "In a BCR/ABL-induced CML-like disease murine model, CD27 was expressed by LSCs (defined as Lin−Sac-1−c-Kithigh) and leukemia progenitors, where CD27 signaling enhanced proliferation and cell cycle progression in a Wnt/β-catenin-dependent manner." (PMID 31186046, 2019). "Similarly to the FLB1 model, we found a significant increase in the percentage of the immature CD27+CD11b— NK cells in both leukemia models." (PMID 34975835, 2021). "CD27 signaling promotes the growth of BCR/ABL+ leukemia cells by activating the Wnt pathway." (PMID 31074387, 2019). "Targeting CD27 on the leukemia stem cells (LSCs) may represent an attractive therapeutic approach in blocking the Wnt/ β-catenin pathway in CML." (PMID 31074387, 2019). "For chronic myelogenous leukemia (CML), it has been reported that the TRAF2-interacting TNFRSF receptor CD27 stimulates the oncogenic Wnt-β-catenin-TNIK-TCF4 pathway, resulting in enhanced proliferation of leukemia stem cells and leukemia progression in a TRAF2-dependent manner." (PMID 36011046, 2022). "Besides its functions in modulating normal HSC self-renewal and differentiation, CD70/CD27 signaling also promotes LSC growth and disease progression in murine model and leukemia patients." (PMID 31186046, 2019). "However, CD27 has also been shown to promote LSC growth and disease progression in leukemia." (PMID 33121189, 2020).
lymphopenia (9 papers, 2014 to 2024). Reduction in the number of lymphocytes. "The phenotypically variable positive cases presented with B and T cell lymphopenia and abnormalities in B and T cell maturation including low naive T cell counts and low CD27+IgD-IgM- switched memory B cells." (PMID 36466816, 2022). "CD27+ memory B cells reach only 25% of baseline at 12 months probably accounting to prolonged T cell lymphopenia since T cell help is required for memory B cell development." (PMID 26204829, 2015). "The finding of CD27+IgD− memory B-cells lymphopenia at cHL diagnosis raises the hypothesis of a preexisting abnormal B-cell subset distribution within peripheral B-cells in HIV-1-infected patients prone to develop cHL." (PMID 35008292, 2021). "Taken together, these data suggest that the elevated mortality of CD19+ B cell, mainly CD19+IgM+ and CD19+CD27− B-cell subsets, may attribute to lymphopenia in active SLE patients." (PMID 25210799, 2014). "CD27+Ly6C− and CD27+Ly6C+ γδ T cells were sorted separately from naive mice and immediately injected into NOD;Rag1−/−;Il2rg−/− (NRG-SGM3) mice to investigate lymphopenia-driven expansion." (PMID 38816652, 2024). "Thus, the death of CD19+CD27− and IgM+CD19+ B cells may be involved in B lymphopenia." (PMID 25210799, 2014).
sarcoidosis (9 papers, 2014 to 2024). Sarcoidosis is a multisystemic disorder of unknown cause characterized by the formation of immune granulomas in involved organs. "An increased count of CD19 + CD5 + CD27– cells in bronchoalveolar lavage has been previously reported in sarcoidosis, thereby confirming the assumption that Breg cells counteract to suppress inflammatory reactions." (PMID 38179278, 2023). "Remarkably, the pattern of peripheral B cell distribution to different subsets, based on IgD vs. CD38 as well as IgD vs. CD27 co-expression in sarcoidosis patients according to available data was very similar to that reported for SS patients." (PMID 31974463, 2020). "On the question of CD27, the research found that the abundant B-cell infiltration in granuloma tissue indicated that B cells were directly involved in the inflammatory process in patients with sarcoidosis." (PMID 36405616, 2022). "Chronic stimulation by persistent foreign antigens or autoantigens lead to T-cell exhaustion, and the dominance of CD27− lymphocytes among sarcoidosis effector CD8+ T-cells supports this notion since CD27 expression on T-cells is lost upon continual antigenic stimulation." (PMID 33036432, 2020). "A recent study noted a higher frequency of peripheral blood B cells in patients with Stage II sarcoidosis compared to healthy controls but noted a reduction in CD19+ CD27+ IgD− class switched and CD19+ CD27+ IgD+ unswitched memory B cell frequencies in active sarcoidosis." (PMID 33036432, 2020). "In further support of this idea, the deficit in sarcoidosis peripheral blood memory B cells has been noted to be mostly due to a decrease in CD27+ IgM+, CD27+ IgG+, or CD27+ IgA+ T-cell-dependent B memory cells, while CD27− IgA+ T-cell-independent B cells increased." (PMID 33036432, 2020). "Also, it has been shown that in patients with sarcoidosis, the increased blood levels of CD27-IgA+ memory B cells are normalized after treatment with infliximab." (PMID 28886017, 2017). "CD21- CD27- B cells are elevated in SLE patients and correlated to disease activity.This elevation is specific to SLE compared to pSS, sarcoidosis and HC (comparison performed in FC)." (PMID 39896815, 2024). "The CD8+ T-cell population of sarcoidosis patients is comprised of fewer CD45RA+ CCR7+ naïve and more CD27− CD28− terminally differentiated effector cells." (PMID 33036432, 2020). "Expression of CD27 and CD39 on FoxP3+ CD4+ T cells was higher in other DPLDs compared to sarcoidosis (P = 0.01 and P = 0.03, resp)." (PMID 24882950, 2014). "Moreover, we found that in sarcoidosis patients there are increased levels of B cell subsets, which were previously shown to display regulatory capacities (CD24+++ CD38+++ and CD5 + CD27−)." (PMID 31974463, 2020). "Further CD8 T cell phenotyping revealed a similar distribution of effector memory subsets according to their CD27 and CD28 expression compared to patients with sarcoidosis (data not shown)." (PMID 33613543, 2020).